CHAC1 (ChaC glutathione specific gamma-glutamylcyclotransferase 1)
Diseases named in the same sentence as CHAC1 in open-access papers (continued):
Sharing a sentence is not in itself a finding about the gene and the disease.
colorectal cancer (4 papers, 2021 to 2025). A primary or metastatic malignant neoplasm that affects the colon or rectum. "Specifically, treatment with a lipid mixture (LM), cholesterol (CHOL), and oleic acid (OA) blocked the increase in CHAC1 expression induced by the ferroptosis inducer RSL3 in colorectal cancer cells." (PMID 39534397, 2024). "Elevated CHAC1 is associated with the induction of ferroptosis, highlighting the role of STAT3 as a modulator of CHAC1 and ferroptosis in colorectal cancer cells." (PMID 39534397, 2024). "STAT3 negatively regulates the expression of CHAC1 in colorectal cancer cells." (PMID 39534397, 2024).
ischemic stroke (4 papers, 2023 to 2024). A stroke disorder caused by obstruction of blood flow to the brain, due to thrombotic (local blood clot formation) or embolic (due to a blood clot or other material traveling from another site) event. "Anti-CHAC1 refers to a therapeutic strategy targeting CHAC1, a key gene associated with ferroptosis in ischemic stroke." (PMID 38385027, 2024). "Bioinformatic analysis identified CHAC1 as a crucial gene in the ferroptosis process in ischemic stroke." (PMID 38385027, 2024). "Subsequently, the expression of CHAC1 and miR-760-3p were confirmed with RT-qPCR in ischemic stroke patients and mice, and the results were consistent with the bioinformatic analysis." (PMID 36967397, 2023). "In the present study, the results of a bioinformatic analysis identified that CHAC1 was a key gene regulating ferroptosis in ischemic stroke, and the microRNAs (miRNAs) that target CHAC1 were predicted." (PMID 36967397, 2023). "According to the bioinformatic analysis, CHAC1 was a key gene in the progress of ferroptosis in ischemic stroke." (PMID 36967397, 2023). "However, in conditions like ischemic stroke and spinal cord injury, CHAC1 promotes neuronal damage by inducing ferroptosis through the depletion of GSH, a critical antioxidant, exacerbating oxidative stress and worsening the injury." (PMID 39534397, 2024). "Thus, we speculated that miR-760-3p/CHAC1 axis exerts vital roles in inhibiting ferroptosis with ADSC-Exo in ischemic stroke, and verified the expression of these two genes in different datasets and tissues from different species." (PMID 36967397, 2023). "In order to explore the molecular mechanism and then identified the potential therapeutic targets for ferroptosis in ischemic stroke, we identified a ferroptosis-related DEG, CHAC1, by analyzing a rare dataset from stroke patients’ brain tissues." (PMID 36967397, 2023).
non-small cell lung carcinoma (4 papers, 2019 to 2025). A group of at least three distinct histological types of lung cancer, including non-small cell squamous cell carcinoma, adenocarcinoma, and large cell carcinoma. "CHAC1 plays a critical role in maintaining mitochondrial function and inducing ferroptosis under conditions of cysteine starvation in non-small cell lung cancer (NSCLC) cells." (PMID 39534397, 2024).
psoriasis (4 papers, 2022 to 2025). An autoimmune condition characterized by red, well-delineated plaques with silvery scales that are usually on the extensor surfaces and scalp. "Thus, our results indicate SLC7A5, SLC7A11, and CHAC1 as the underlying biomarkers for psoriasis, providing further evidence about the crucial role of ferroptosis in psoriasis." (PMID 36276287, 2022). "However, the possible mechanisms underlying CHAC1 dysregulation in skin epithelial cells during AA and psoriasis development remained to be elucidated." (PMID 35983595, 2022). "Similar to the results of paired samples in the GSE30999 dataset, the expression levels of SLC7A5, SLC7A11, and CHAC1 were increased in the psoriasis lesions (1.85-, 1.73- and 1.70-fold, respectively) compared to normal skin tissues." (PMID 36276287, 2022). "Recent research has highlighted that CHAC1 may influence the development of psoriasis by regulating ferroptosis, suggesting its potential as a biomarker for this condition." (PMID 41385507, 2025). "Our analysis revealed the upregulation of 3 ferroptosis markers (Chac1, Slc40a1, Fth1) and 29 ferroptosis drivers (including Alox12B and Alox15B, which encodes 15-LOX-2) as well as downregulation of 7 ferroptosis suppressors in psoriasis." (PMID 39570671, 2024). "However, the role of CHAC1 in the execution of ferroptosis and its involvement in psoriasis is unclear." (PMID 36276287, 2022). "SLC7A5, SLC7A11, and CHAC1 may affect the development of psoriasis by regulating ferroptosis." (PMID 36276287, 2022). "Besides that, using another ten data sets, we showed that CHAC1 could clearly distinguish AA from similar clinical phenotypes, such as scarring alopecia due to psoriasis." (PMID 35983595, 2022). "Our findings further supported the involvement of Chac1 in UPR-related processes and its relevance to psoriasis pathogenesis." (PMID 41385507, 2025). "All selected hub genes present a similar expression pattern among AA, psoriasis, and AGA data sets, except four genes, including CHAC1, COMP, and HOXC13." (PMID 35983595, 2022).
triple-negative breast carcinoma (4 papers, 2017 to 2023). An invasive breast carcinoma which is negative for expression of estrogen receptor (ER), progesterone receptor (PR), and human epidermal growth factor receptor 2 (HER2). "ChaC glutathione-specific gamma-glutamyl cyclotransferase 1 (CHAC1) degradation of glutathione enhances cystine starvation-induced ferroptosis in triple-negative breast cancer cells via the GCN2-eIF2α-ATF4 pathway." (PMID 33672990, 2021). "GSH levels are reduced due to cystine-starvation in triple-negative breast cancer cells, suggesting that CHAC1 acts as an oncogene in triple-negative breast cancer, which is consistent with the findings of our AML study." (PMID 35111195, 2021). "In line with our findings, CHAC1 was reported to be induced by cystine starvation, promote GSH degradation and enhance cystine starvation-induced cell death in human triple-negative breast cancer cells." (PMID 37553341, 2023).
bladder cancer (3 papers, 2024 to 2025). "CHAC1 is crucial in inducing ferroptosis in bladder cancer (Bca) cells." (PMID 39534397, 2024). "Critical knowledge gaps persist regarding CHAC1’s role in urothelial carcinomas (e.g., bladder cancer), where mechanistic investigations remain absent." (PMID 40860820, 2025). "Additionally, CHAC1 downregulation results in increased levels of ferroptosis inhibitors such as GPX4 and SLC7A11, underscoring its pivotal role in controlling ferroptosis and its potential as a therapeutic target in bladder cancer." (PMID 39534397, 2024).
diabetes (3 papers, 2024 to 2025). "Two other genes involved in the glutathione metabolism pathway, CHAC1 and GGT7, were also found to be associated with four different aging outcomes (CHAC1 was associated with frailty index, diabetes, COPD, and BMI; GGT7 was associated with father’s age at death, endometrial cancer and BMI)." (PMID 39398990, 2025). "Metabolic disorders such as diabetes are also affected by CHAC1’s role in β-cell survival." (PMID 39534397, 2024). "Furthermore, the involvement of CHAC1 in non-malignant diseases, such as diabetes, liver injury, and respiratory disorders, adds complexity, as its therapeutic modulation could potentially worsen these conditions by disrupting GSHmetabolism and increasing oxidative stress." (PMID 39534397, 2024).
head and neck squamous cell carcinoma (3 papers, 2021 to 2025). A squamous cell carcinoma that arises from any of the following anatomic sites: lip and oral cavity, nasal cavity, paranasal sinuses, pharynx, larynx, and salivary glands. "A distinct mode of action has been detected in head and neck squamous cell carcinoma (HNSCC) cells, in which nisin highly upregulated the γ-glutamyl cyclotransferase (CHAC1), a known regulator of cation transport and apoptosis." (PMID 41395610, 2025).
lung adenocarcinoma (3 papers, 2021 to 2024). A carcinoma that arises from the lung and is characterized by the presence of malignant glandular epithelial cells. "Specifically, UCA1 is found to be highly expressed in cisplatin-resistant lung adenocarcinoma cells, and its expression correlates with the downregulation of several mRNAs, including ChaC1." (PMID 39534397, 2024). "The downregulation of ChaC1, along with other genes, appears to contribute to the mechanisms by which lung adenocarcinoma cells develop resistance to cisplatin, highlighting the UCA1-TXNIP axis as a potential therapeutic target for overcoming drug resistance." (PMID 39534397, 2024). "Research on the role of lncRNA UCA1 in cisplatin resistance in lung adenocarcinoma outlines several mechanisms through which UCA1 influences the expression of various genes, including ChaC1." (PMID 39534397, 2024).
neuroblastoma (3 papers, 2018 to 2023). Neuroblastoma (NB) is the most common solid, extracranial childhood tumor. "As the immunofluorescence showed the co-localization of NeuN with CHAC1 obviously, we further evaluated the systematic effect of ADSC-Exo in an oxygen–glucose deprivation (OGD) mouse neuroblastoma cell line N2a model." (PMID 36967397, 2023). "On the other hand, we first identified CRELD2 as a novel ER stress-inducible gene using microarray analysis of Tg-treated mouse neuroblastoma cell-line, Neuro2a3, and have been employing this Neuro2a cells to elucidate several ER stress gene expression (e.g., MANF, Chac1 and GADD153) in detail." (PMID 30111858, 2018).
renal fibrosis (3 papers, 2022 to 2025). A final common manifestation of a wide variety of chronic kidney diseases characterized by glomerulosclerosis and tubulointerstitial fibrosis. "And the Masson staining and α‐SMA staining demonstrated that the degree of renal fibrosis induced by CaOx crystals was diminished benefitting from CHAC1 knockdown." (PMID 39836526, 2025). "Inhibition of ERS or knockdown of CHAC1 significantly restored GSH levels, reduced ferroptosis marker accumulation, and markedly decreased renal fibrosis and crystal deposition, confirming the critical role of the ERS-CHAC1-GSH axis in kidney stone formation." (PMID 40909330, 2025).
breast tumors (2 papers, 2012 to 2023). "We compared the expression profiles of 272 ERS-related genes in primary breast tumors and normal breast tissue and identified FBXO6, PMAIP1, ERP27, and CHAC1 as independent prognostic factors with established risk models (defining the risk scores as ERScore) and model validation." (PMID 37313465, 2023).
Cerebral ischemia (2 papers, 2023 to 2025). Restriction of arterial blood supply to the brain associated with insufficient oxygenation to support the metabolic requirements of the tissue. "Regarding miR-760-3p, studies have shown that it can activate the NF-kB pathway in cerebral ischemia by regulating Map3k8 and can inhibit ferroptosis by targeting CHAC1 in neurons." (PMID 40427763, 2025). "Collectively, the present study successfully designed and prepared anti-CHAC1 ADSC-Exo and suggested a promising exosome-based strategy for anti-ferroptosis therapy in cerebral ischemia/reperfusion injury." (PMID 36967397, 2023).
colon cancer (2 papers, 2023 to 2025). "MES exposure in colon cancer cells resulted in changes in the expression of 56 ferroptosis-related genes, including ferroptosis markers such as PTGS2 and CHAC1." (PMID 39857803, 2025).
heart failure (2 papers, 2023). Inability of the heart to pump blood at an adequate rate to meet tissue metabolic requirements. "Considering that glutathione is a crucial intracellular antioxidant, several studies showed that the dysregulation of Chac1 alters intracellular glutathione expression and is associated with various diseases, such as cancer and heart failure." (PMID 36675091, 2023).
kidney cancer (2 papers, 2021 to 2025). Primary or metastatic malignant neoplasm involving the kidney. "Future research should delve deeper into the specific mechanisms of CHAC1 at different stages of kidney cancer and investigate how to utilize its expression level to optimize personalized treatment plans and improve the survival rate of kidney cancer patients." (PMID 40860820, 2025). "Furthermore, we performed experiments in vitro to demonstrate the function of CHAC1 in kidney cancer cell lines using overexpression vector of CHAC1." (PMID 33728749, 2021). "Similarly, other reports indicate that ChaC1 overexpression may be related to dedifferentiation, proliferation, invasion, and migration of kidney cancer cells, thereby reducing patient survival rates." (PMID 40860820, 2025).
kidney stone (2 papers, 2025). "For urine volume and urine PH, the mouse kidney stone model both showed a marked decline, while CHAC1 deficiency alleviated the urine volume and urine PH, to a certain degree." (PMID 39836526, 2025). "The knockdown of CHAC1 significantly reversed the GPX4 and XCT protein deficiency in the mouse kidney stone model, and the upregulation of ACSL4 and CD71 protein was also mildly regained." (PMID 39836526, 2025). "To further validate the mechanism of CHAC1 in CaOx kidney stones, we injected AAV‐sh‐CHAC1 30 days in advance to inhibit CHAC1 expression in the kidneys before establishing mouse kidney stone models." (PMID 39836526, 2025). "We found that the content of Fe2+ and the level of 4‐HNE were effectively diminished due to CHAC1 knockdown in mouse kidney stone models compared to the stone model group." (PMID 39836526, 2025). "It is assumed that the inhibition of CHAC1 can reduce the pro‐apoptotic effect and ferroptosis induced by ER stress at the same time, which will greatly promote the basic and clinical research on the prevention and treatment of kidney stones." (PMID 39836526, 2025). "And in kidney stone mouse model, renal expression of CHAC1 was apparently increased." (PMID 39836526, 2025). "Then, the indicators of renal impairment, Kim‐1 and NGAL, were measured and our results showed that CHAC1 knockdown in normal mouse also did not cause kidney injury, but in mouse kidney stone models could mildly alleviate renal impairment." (PMID 39836526, 2025). "Similarly, based on the proteomics data and the nephrolithiasis gene expression dataset analysis, the gene expression correlation analysis indicated that CHAC1 may play an important role in mediating ER stress‐dependent ferroptosis in CaOx kidney stone formation." (PMID 39836526, 2025). "And we further used the nephrolithiasis gene expression datasets (GSE73680), which found a strong negative association between GPX4 and CHAC1." (PMID 39836526, 2025).
ovarian tumor (2 papers, 2023 to 2024). "The expression level of CHAC1 is also correlated with a more advanced stage and poorer prognosis in breast and ovarian tumors." (PMID 37299011, 2023). "CHAC1, a biomarker for ferroptosis, was highly induced in both OVCAR-8 and NCI/ADR-RES ovarian tumor cells." (PMID 39201357, 2024).
pancreatic cancer (2 papers, 2023 to 2025). "We further performed qRT-PCR on five selected ferroptosis-related genes (HMOX1, CHAC1, SLC3A2, SLC7A11, and FTH1) in pancreatic cancer cells after 12 and 24 h of CBC treatment." (PMID 40790027, 2025).
sarcoma (2 papers, 2021 to 2023). A usually aggressive malignant neoplasm of the soft tissue or bone. "Using TCGA datasets, we have also demonstrated that the high expression of CHAC1 was associated with a worse prognosis in sarcoma patients, suggesting that CHAC1 can play a role in RMS tumorigenesis." (PMID 36816948, 2023).
stomach cancer (2 papers, 2020 to 2022). "Conversely, DDIT4, NDRG1, and CHAC1 showed lower levels in stomach tumor tissues than that in normal tissues." (PMID 32457731, 2020).
Stroke (2 papers, 2023 to 2025). Sudden impairment of blood flow to a part of the brain due to occlusion or rupture of an artery to the brain. "Overexpression of CHAC1/BOTCH also demonstrated notable rescue effects against neuronal injury, highlighting its potential as a therapeutic target in stroke and neuroinflammation research." (PMID 41488051, 2025). "The high expression of CHAC1 was further validated in datasets from stroke patient’s infarct core (p < 0.05), mouse ischemic cortex (p < 0.05), and blood samples of patients (p < 0.01)." (PMID 36967397, 2023). "CHAC1 was reported to be a ferroptosis-related gene, and mainly explored in various cancers, while no related finding was reported in stroke disease." (PMID 36967397, 2023).
viral infection (2 papers, 2013 to 2024). "The repression of CHAC1 expression may inhibit host apoptosis to facilitate DHAV-C replication in viral infection." (PMID 23923051, 2013). "CHAC1 expression was modestly increased by Type I interferon, but increased much more with viral infection, a finding that suggests CHAC1 is not primarily an interferon-stimulated gene." (PMID 38635661, 2024).
age-related macular degeneration (1 paper, 2025). Age-related loss of vision in the central portion of the retina (macula), secondary to retinal degeneration. "CHAC1 has recently been implicated in age-related macular degeneration and muscle wasting." (PMID 40792619, 2025).
alopecia (1 paper, 2022). Hair loss usually from the scalp. "Among them, the CHAC1 gene has the potential to distinguish Psoriatic alopecia from AA and can be used for the determination of alopecia severity." (PMID 35983595, 2022).
atherosclerosis (1 paper, 2024). A disease characterized by the build-up of fatty material and calcium deposition in the arterial wall resulting in partial or complete occlusion of the arterial lumen. "In liver injury, CHAC1’s promotion of GSHdegradation accelerates oxidative stress and liver cell death, while in atherosclerosis, it contributes to plaque instability by promoting apoptosis in lesional macrophages and smooth muscle cells." (PMID 39534397, 2024). "CHAC1’s role in acute liver injury and atherosclerosis further underscores its involvement in inflammatory and apoptotic pathways." (PMID 39534397, 2024).
B-cell acute lymphoblastic leukemia (1 paper, 2022). A neoplasm of lymphoblasts committed to the B-cell lineage, typically composed of small to medium-sized blast cells. "In B-cell acute lymphoblastic leukemia, CHAC1 can overcome drug resistance and exert anti-leukemic activity." (PMID 36338716, 2022).
Cachexia (1 paper, 2023). Severe weight loss, wasting of muscle, loss of appetite, and general debility related to a chronic disease. "In this study, we tested the hypothesis that CHAC1 inhibition may preserve the intracellular glutathione in skeletal muscles and thus represent a novel strategy to treat muscle wasting in cachexia conditions." (PMID 37014882, 2023). "Importantly, we found that CHAC1 expression is significantly upregulated in skeletal muscles under various wasting conditions, including cancer induced cachexia, chemo-agent cisplatin induced cachexia, and fasting induced muscle atrophy." (PMID 37014882, 2023). "Unfortunately, neither Pan02 cancer nor cisplatin induced cachexia model was found to manifest significantly impaired muscle function (data not shown) and thus not suitable to test the effect of CHAC1 inactivation on muscle function." (PMID 37014882, 2023).
cardiomyopathy (1 paper, 2023). A disease of the heart muscle or myocardium proper. "Genes associated with ER stress (e.g., ATF4, NUPR1, DDIT3, TRIB3, CHAC1, SESN2, HERPUD1) were upregulated and genes related to cardiomyopathy and sarcomeric structure (e.g., MYH7, SYNPO2L, LDB3, ACTN2, MYLK3) were downregulated by afatinib, sorafenib, or high-dose ponatinib." (PMID 37069550, 2023).
Chlamydia infection (1 paper, 2014). "Our results showed that the impact of Chlamydia infection on apoptosis (BIRC3, EMP1, CHAC1), immune response, host cell structure and cell cycle in EEC is similar to what has been observed in epithelial cells." (PMID 24959205, 2014).
chronic heart failure (1 paper, 2023). "In our model of chronic heart failure, mRNA expression of the ferroptosis marker Chac1 was also increased and ameliorated by NMN administration." (PMID 37793777, 2023).